AS3MT (arsenite methyltransferase)
Description:
Catalyzes the transfer of a methyl group from AdoMet to trivalent arsenicals producing methylated and dimethylated arsenicals. It methylates arsenite to form methylarsonate, Me-AsO(3)H(2), which is reduced by methylarsonate reductase to methylarsonite, Me-As(OH)2. Methylarsonite is also a substrate and it is converted into the much less toxic compound dimethylarsinate (cacodylate), Me(2)As(O)-OH.
Synonyms: CYT19
Tractability: Small molecule: a high-quality ligand is known. PROTAC: ubiquitination databases record sites on it; a small molecule that binds it is known.
Target class: Enzyme; Transferase
Gene: Protein-coding gene on chromosome 10 (102,869,470 to 102,901,899, forward strand). Ensembl gene ENSG00000214435.
Subcellular location: Cytoplasm, cytosol
Subcellular location (Human Protein Atlas): Mitochondria
Pathways (Reactome):
Metabolism: Methylation
Gene Ontology:
Molecular function: arsenite methyltransferase activity
Biological process: arsonoacetate metabolic process; methylation; toxin metabolic process
Cellular component: cytosol
Genetic constraint (gnomAD): Loss-of-function variants: 41 observed, 42.22 expected, observed/expected ratio (o/e) 0.97, 90% interval 0.75 to 1.26. The upper end of that interval is the gene's LOEUF score, 1.26, which puts it in group 5 of 6, group 1 being the genes least tolerant of losing a copy. Missense variants: 365 observed, 439.58 expected, observed/expected ratio (o/e) 0.83, 90% interval 0.76 to 0.9. Synonymous variants: 131 observed, 150.74 expected, observed/expected ratio (o/e) 0.87, 90% interval 0.75 to 1.
Homologues: Orthologues: chimpanzee AS3MT (99% identical), macaque AS3MT (97% identical), pig AS3MT (84% identical), rabbit AS3MT (83% identical), mouse As3mt (77% identical), rat As3mt (76% identical), tropical clawed frog as3mt.2 (59% identical), zebrafish as3mt (51% identical), Caenorhabditis elegans rips-1 (14% identical), Caenorhabditis elegans R08F11.4 (13% identical), Caenorhabditis elegans K12D9.1 (12% identical), Caenorhabditis elegans R08E5.1 (11% identical). Paralogues in human: COQ5 (14% identical), TMT1A (11% identical), METTL27 (11% identical), TMT1B (10% identical).